ENSG00000302371 (novel transcript, antisense to ORAI1)
Gene: Long non-coding RNA gene on chromosome 12 (121,590,413 to 121,627,084, reverse strand). Ensembl gene ENSG00000302371.
Gene Ontology:
Molecular function: U4 snRNA binding
Biological process: formation of quadruple SL/U4/U5/U6 snRNP; spliceosomal tri-snRNP complex assembly
Cellular component: U4/U6 x U5 tri-snRNP complex; U6 snRNP